LRP1 (LDL receptor related protein 1)
Diseases named in the same sentence as LRP1 in open-access papers (continued):
Sharing a sentence is not in itself a finding about the gene and the disease.
neurodegenerative disease (23 papers, 2014 to 2025). A disorder of the central nervous system characterized by gradual and progressive loss of neural tissue and neurologic function. "LRP1 is highly expressed in multiple brain cells, including neurons, astrocytes, and microglia, and is implicated in normal neurodevelopment and multiple neurodegenerative diseases (27, –, 31)." (PMID 41313001, 2025). "In the aging brain, decreased Lrp1 levels are associated with impaired clearance of Aβ and reduced synaptic plasticity, leading to cognitive decline and an increased risk of neurodegenerative diseases [1397, 1400]." (PMID 40407975, 2025). "LRP1 is a surface endocytic receptor that binds and internalizes extracellular ligands for lysosomal degradation and has recently been implicated in the development of neurodegenerative diseases." (PMID 37308987, 2023). "Thus, further studies on the interaction between SA and LRP1 seem warranted, particularly in regard to LRP1’s association with neurodegenerative diseases, such as Alzheimer’s57,58." (PMID 31511554, 2019). "Restoration of LRP1 expression in microglia may serve as a novel therapeutic approach to combat microglial dysfunction associated with chronic inflammation in neurodegenerative diseases including AD." (PMID 27931217, 2016). "Another pathological symptom of neurodegenerative diseases is a decreasing level of the protein LRP1 or of AChE itself." (PMID 35739872, 2022). "Consistently, LRP1 expression is decreasing with age in brain microvasculature and liver, while ageing increases the incidence of the progressive neurodegenerative disease." (PMID 35344086, 2022). "The crucial anti-inflammatory role of LRP1 in counteracting deleterious effects of neurodegenerative diseases has been previously reported." (PMID 26031516, 2015). "Thus, by using cortical neurons in primary culture we next investigated the mechanisms by which the expression of LRP1-ICD was increased after NMDA-induced neurotoxicity, which has been implicated in a variety of neurodegenerative diseases." (PMID 31409872, 2019). "Since synaptic dysfunction is a common feature of neurodegenerative diseases including AD, our findings might provide clues as to how the LRP1-GluA1 pathway can be targeted for therapy." (PMID 25500815, 2014). "They further demonstrate that LRP1-GluA1 pathway may hold promises as a therapeutic target for restoring synaptic functions in neurodegenerative diseases." (PMID 25500815, 2014). "Collectively, our results show that targeting LRP1 to improve mitochondrial function is a potential pharmacotherapeutic strategy against oxidative damage in TBI and other neurodegenerative diseases." (PMID 37408279, 2023). "Thus, our results indicate that LRP1 controls GluA1-mediated synaptic formation, integrity and function, and disturbances of this pathway may be partially involved in synaptic deficits in neurodegenerative diseases." (PMID 25500815, 2014). "Hence, targeting LRP1 could be a potential strategy against oxidative stress in TBI and possibly other neurodegenerative diseases." (PMID 37408279, 2023).
cardiovascular disease (12 papers, 2010 to 2023). "In addition to its endocytosis function in lipoprotein metabolism and homeostasis of proteases involved in matrix modulation, LRP-1 also regulates the pathogenesis and progression of cardiovascular disease through various signaling mechanisms." (PMID 25514242, 2014). "Thus, the exact in vivo role of fibroblast LRP-1 signaling in cardiovascular disease remains to be elucidated." (PMID 25514242, 2014). "The aim of this study was to characterize the LRP1 expression level in circulating monocytes of individuals with SCA and compared with individuals with low (LR) and intermediate (IR) risk of cardiovascular diseases, both without evidence of atherosclerotic lesions in carotid and coronary arteries." (PMID 35958411, 2022).
metabolic disease (5 papers, 2021 to 2023). A congenital disorder (due to inherited enzyme abnormality) or acquired (due to failure of a metabolically important organ) disorder resulting from an abnormal metabolic process. "Most of the information regarding how LRP1 dysfunction may increase metabolic disease risk is inferred from in vitro cell culture experiments or in vivo studies with conditional knockout mice with tissue-specific LRP1 deficiency." (PMID 33500241, 2021). "This study took advantage of the availability of LRP1 knock-in mice carrying an inactivating mutation in the distal NPxY motif to examine the consequence of global LRP1 dysfunction in diet-induced metabolic diseases." (PMID 33500241, 2021). "These large-scale population studies suggested that LRP1 dysfunction may contribute directly to metabolic disease advancement." (PMID 33500241, 2021). "The LRP1 NPxY mutant mouse phenotype differs from phenotypes observed in mice with tissue-specific LRP1 inactivation, thus highlighting the importance of an integrative approach to evaluate how global LRP1 dysfunction contributes to metabolic disease development." (PMID 33500241, 2021). "Meanwhile, the core genes in the Lean line might be Nf2 (linking syndromic, nervous, urinary and cellular proliferative diseases), Lrp1 (linking cardiovascular and nervous system diseases and physical disorders), and Ifngr2 (linking immune, endocrine and metabolic diseases)." (PMID 36414820, 2023).
neurological disease (4 papers, 2023 to 2025). "This is supported by several studies reporting an important role of Trem2 and Lrp1 in phagocytosis and neuroprotection in neurological disease." (PMID 38155863, 2023).
retinopathies (4 papers, 2013 to 2024). "Unravelling this molecular mechanism is paramount, as LRP1 levels at the PM may be associated with MGCs activation and migration, representing a potential therapeutic target for retinopathies." (PMID 31519919, 2019). "In addition, in human eyes with retinopathies, LRP1 expression was reduced in RPE-Bruch’s membrane-choriocapillaris complex and choroidal stroma." (PMID 39456672, 2024). "In this sense, our results show that the migratory capacity of MIO-M1 cells induced by α2M* depends on the intracellular distribution and traffic of LRP1 to the PM, which may have special clinical connotations in the treatment of proliferative retinopathies." (PMID 31519919, 2019). "Moreover, in a mouse oxygen-induced retinopathy model, specific depletion of LRP1 in endothelial cells results in abnormal development of neovessels." (PMID 28589128, 2017).
adenocarcinoma (3 papers, 2018 to 2022). A common cancer characterized by the presence of malignant glandular cells. "LCM analyses revealed that LRP1 mRNA expression was 5.1-fold lower in adenocarcinoma cells than in stromal cells." (PMID 29507659, 2018). "To explore LRP1 epigenetic modifications, we analyzed both intronic and promoter methylation on available fresh frozen samples of 64 adenocarcinomas and 39 normal colon mucosa." (PMID 29507659, 2018). "First, qRT-PCR, LCM and IHC analyses revealed that LRP1 was significantly lower expressed in adenocarcinoma cells than in normal mucosa and stromal cells." (PMID 29507659, 2018). "In adenocarcinoma, LRP1 was expressed in malignant cells in 244/307 (79%) of the cases." (PMID 29507659, 2018). "In these adenocarcinoma samples, stromal fibroblasts expressed LRP1 in all cases." (PMID 29507659, 2018). "LRP1 was overexpressed when compared with paired normal colon samples in only 9/85 adenocarcinoma cases (10.6%; data not shown)." (PMID 29507659, 2018).
bacterial infection (2 papers, 2021 to 2024). "During bacterial infection, to restrict the bacteria from iron acquisition, macrophages take up iron via receptors including hemoglobin‐haptoglobin receptor (CD163), transferrin receptor (TfR) and lipoprotein receptor‐related protein 1 (LRP1)." (PMID 38247172, 2024).
inflammation (2 papers, 2021 to 2024). Aberrant reaction of the microcirculation characterized by movement of fluid and leukocytes from the blood into extravascular tissues. "Studies also revealed the association of lipocalin-2 (LCN2) and low-density lipoprotein receptor-related protein-1 (LRP1) with intestinal inflammation." (PMID 34423140, 2021). "Low-density lipoprotein receptor-related protein 1 (LRP1), also known as scavenger receptor class L (SR-L), mediates the clearance of apoptotic neutrophils by resident alveolar macrophages, thereby suppressing the development of lung inflammation." (PMID 38807426, 2024).
hematological diseases (1 paper, 2023). "In this review, we provide a detailed discussion of the diverse role of LRP1 in both innate and adaptive immune cell types, and how this molecule may serve as a potential target in hematological diseases." (PMID 37020553, 2023).
immune diseases (1 paper, 2014). "Clearly, it will be of interest to ascertain at the genetic level whether loss-of-function mutations occur at CD91/LRP1 or SCARF1 receptor loci that result in risk associations for human auto-immune diseases." (PMID 25426118, 2014).
kidney disease (1 paper, 2014). "In this review, we focus on the current understanding of LRP-1 signaling and its roles in the development and progression of kidney disease." (PMID 25514242, 2014).
LRP1 also shares sentences with these, for which no sentence is quoted: Glucose intolerance (7 papers); acute myocardial infarction (4); Parkinson disease (4); psoriasis (3); Colon (2); Coronary artery dissection (2); depression (2); Dystonia (2); fibromuscular dysplasia (2); liposarcoma (2); malignant glioma (2); medulloblastoma (2); spinal cord injury (2); Stomach Adenocarcinoma (2); Tremor (2); vitamin A deficiency (2); acute myeloid leukemia (1); acute pancreatitis (1); age (1); AIDS (1); airway hyperresponsiveness (1); Allergy (1); Aortic Insufficiency (1); arrhythmogenic right ventricular cardiomyopathy (1); Atherosclerotic lesion (1); atopic dermatitis (1); autoimmune disease (1); bone sarcoma (1); brain diseases (1); brain glioblastoma (1).
A further 73 diseases each share a sentence with LRP1 in 1 paper.